INS (insulin)
Diseases named in the same sentence as INS in open-access papers (continued):
Sharing a sentence is not in itself a finding about the gene and the disease.
diabetes (continued). "Reported data represents the observed association between use of insulin secretagogues preceding breast cancer and the growth factor profiles at the time of cancer diagnosis in women with diabetes mellitus." (PMID 28289695, 2017). "Reported data represents the observed association between use of injectable insulin preceding breast cancer and the pro-inflammatory C–C chemokine profiles at the time of cancer diagnosis in women with diabetes mellitus." (PMID 28289694, 2017). "The American Diabetes Association recommends combined use of different insulin products for children with Type 1 Diabetes and in adults whose blood glucose level is difficult to control." (PMID 28836974, 2017). "Types 1 and 2 diabetes are conditions with very different aetiology and pathogenesis, but many people with long-duration type 2 diabetes require insulin treatment, and the risk of cardiovascular disease is high in both conditions." (PMID 28770327, 2017). "Visceral obesity is thought to be directly linked to deterioration of insulin sensitivity, increased risk of developing diabetes, and more specifically, “high-TG/low HDL-C dyslipidemia”33." (PMID 28821853, 2017). "GDM is associated with both insulin resistance and impaired insulin secretion and shares the same risk factors with Type 2 diabetes mellitus (T2DM)." (PMID 28644881, 2017). "Here, we performed a genetic study of a girl born to consanguineous parents, affected by juvenile-onset insulin-treated diabetes associated with congenital cataract." (PMID 29112131, 2017). "Pathological features of AD, including tau phosphorylation and amyloid plaque deposition, were exaggerated in the brains of APP transgenic mice following the induction of insulin-deficient diabetes." (PMID 28422052, 2017). "Obesity and diabetes are both associated with peripheral tissue insulin resistance, which results in an increase of insulin levels to overcome this peripheral resistance." (PMID 29383194, 2017). "The lack of knowledge about diabetes demonstrated by the participating children was related to insulin function, causes of diabetes, and the role of foods in the body." (PMID 30291061, 2017). "In patients presenting with Diabetes Mellitus (DM), chronic hyperglycaemia is apparent where glycaemic control is severely impaired as a result of a deficiency in insulin or its action." (PMID 28779138, 2017). "The loss of residual insulin secretion is, next to diabetes duration, related to the age at diabetes onset." (PMID 28534863, 2017). "Intriguingly, intravenous administration of synthetic mimics of these miRNAs promoted β-cell proliferation after STZ treatment, thereby achieving recovery from insulin-deficient diabetes." (PMID 27974246, 2017). "For women with diabetes taking insulin, we found a positive association with MD in all models, although statistically non-significant, due to small numbers (2.08; 0.68–6.35)." (PMID 27832382, 2017). "Animal experiments found that Mg deficiency was associated with reduced glucose uptake and utilization in insulin-sensitive tissues, thus promoting insulin resistance and the development of diabetes." (PMID 28927411, 2017). "It has been found that circulating concentrations of adiponectin were decreased in the subjects who were obese or resistant to insulin and obese rhesus monkeys that were at high risk for diabetes." (PMID 28786989, 2017). "Increased long-chain acylcarnitine levels have also been associated with insulin resistance with diabetes, possibly via interference of insulin signaling within the cell membrane, while this relation is less clear for short-chain acylcarnitines." (PMID 29121091, 2017). "Diabetes mellitus is a metabolic dysfunction characterised by high concentrations of glucose within blood (termed hyperglycaemia), which is caused by deficits in insulin production and activity and/or cellular resistance to insulin." (PMID 28616080, 2017).
diabetes (continued). "The main cause of diabetes is either insufficient production of insulin by the pancreas or the failure of the body cells to properly respond to this hormone (Bonen, Chabowski, Luiken, & Glatz, 2007; Pociot & Lernmark, 2016)." (PMID 28369933, 2017). "Type 1 diabetes mellitus (previously called insulin-dependent diabetes mellitus or juvenile or childhood-onset diabetes mellitus) is characterized by deficient insulin production and requires daily administration of insulin." (PMID 29295509, 2017). "T2DM, however, is commonly associated with the inability of cells to respond to insulin (insulin resistance) and hence referred as non-insulin dependent diabetes mellitus (NIDDM)." (PMID 28770011, 2017). "Having diabetes controlled by diet or oral antidiabetic agents is associated with a decrease in MD, whereas taking insulin is associated with an increase in MD." (PMID 27832382, 2017). "The strong associations between metabolic-related markers, including insulin, and self-reported diabetes confirms that the assay works." (PMID 28753646, 2017). "The nut intake effect on glucose and insulin levels and diabetes risk has also been previously investigated." (PMID 29182576, 2017). "Caused by multiple aetiology, diabetes mellitus is a metabolic disorder which is characterized by chronic hyperglycemia resulting from the deficiency of insulin secretion and/or insulin action." (PMID 29234435, 2017). "More recently, the GUaRDIAN (Genetics Underlying Diabetes in Hispanics) Consortium was formed in order to characterize the genetic components of insulin sensitivity, insulin secretion, insulin clearance, and glucose effectiveness in 4,176 Mexican Americans." (PMID 29376044, 2017). "Diabetes mellitus (DM) is a complex chronic illness associated with a state of high blood glucose level, or hyperglycemia, occurring from deficiencies in insulin secretion, action, or both." (PMID 28167928, 2017). "It is noteworthy that studies investigating the association of dietary protein with insulin/glucose homeostasis, as well as the risk of dysglycemia and diabetes, have generated mixed results." (PMID 28869547, 2017). "Alterations in glucose metabolism have been previously linked to the E2F/Rb pathway as demonstrated by double knock-out of E2F1/E2F2 which impaired insulin production and caused diabetes." (PMID 28085920, 2017). "Type 2 diabetes mellitus (T2D), the most common form of diabetes mellitus (DM) accounting for 80–90% of the cases, is a chronic polygenic disorder identified by defects in insulin action and/or deficiencies in pancreatic insulin secretion." (PMID 28812028, 2017). "In summary, the approach allows users to model reliable estimates of risk and cost changes associated with HbA1c changes in insulin-treated diabetes populations." (PMID 27510441, 2017). "On the other hand, a recent study reported that the occurrence of hypoglycemia was associated with increased risk of CVD and all-cause mortality in insulin-treated patients with type 1 diabetes mellitus (T1DM) and T2DM5." (PMID 28067320, 2017). "Premorbid insulin-requiring diabetes was independently associated with lower admission c-peptide, whereas greater plasma creatinine was independently associated with higher levels." (PMID 28497374, 2017). "Diabetes mellitus (DM) is a chronic metabolic disease caused by diminished or absent secretion of insulin or even by reduced tissue sensitivity to insulin." (PMID 28699985, 2017). "After performing multivariate regression analysis, we found that age, duration of diabetes, insulin therapy, SBP, HbA1c, and ACR were significantly associated with DR." (PMID 28924157, 2017). "Multiple autoantibodies and strong HLA risk are associated with a severe loss of insulin secretory capacity and rapid progression to diabetes." (PMID 28829396, 2017). "Especially the use of insulin is experienced as a problem by these patients as it is associated with severe diabetes-related complications." (PMID 29326916, 2017).
diabetes (continued). "Analysis restricted to the NHL and lung cancer studies, from which all specimens analyzed were collected at baseline, revealed similar associations between self-reported diabetes and insulin and GIP." (PMID 28753646, 2017). "The complications encountered in type 2 diabetes mellitus seems to be associated with the threshold level of basal insulin." (PMID 28529547, 2017). "On the other hand, the disruption of IRS2 impaired peripheral insulin signaling and pancreatic β-cell function, and these incomplete signaling pathways finally caused diabetes." (PMID 28282409, 2017). "The insulin/SREBP-1/transgelin-2 network should be further explored as a diagnostic marker or a novel therapeutic target for diabetes-associated PDAC." (PMID 28521289, 2017). "A deficiency in insulin results in diabetes, a major economic and primary health care burden across both developed and developing countries." (PMID 29222417, 2017). "Diabetes is a major chronic systemic metabolic disease resulting from the dysfunction of carbohydrate metabolism due to a relative deficiency of insulin." (PMID 28750064, 2017). "In Model 2, serum Mg was positively associated with age and household income and negatively associated with diabetes and serum glucose and insulin concentrations." (PMID 28304338, 2017). "In fact there are reports that super tight glucose control with insulin Rx increases risk for hypoglycemic episodes, and repeated hypoglycemic episodes have been implicated as part of the diabetes-dementia syndrome." (PMID 28140402, 2017). "In the final predictive risk score were included several variables, as insulin treatment during pregnancy, family history of diabetes, BMI in early pregnancy, lactation, and maternal age at delivery." (PMID 28133617, 2017). "Extensive mapping of this region associates variable number of tandem repeats in the 5′ promoter of INS with diabetes risk." (PMID 28959234, 2017). "In those two studies, cg06500161 was positively associated with diabetes-related traits including fasting glucose, HbA1c, fasting insulin and HOMA-IR." (PMID 28869506, 2017). "A recent study reported that insulin-treated diabetes was an independent risk factor for respiratory distress in neonates born after 33 weeks in a group of women with pregestational diabetes or GDM." (PMID 28197657, 2017). "Adiposity increases the risk of diabetes and reduces insulin sensitivity through the fat tissue release inflammatory markers, insulin-like growth factors (IGF), sCD163 and adipokines." (PMID 28673352, 2017). "Poor prescribing practice, as evidenced by ambiguous dosing of insulin, was the most common PI associated with drugs used in diabetes in this study." (PMID 29077019, 2017). "Type 1 diabetes (T1D) is an autoimmune disease, characterized by destruction of insulin producing cells in the pancreas resulting in absolute deficiency of insulin (Standards of Medical Care in Diabetes, 2017)." (PMID 28993722, 2017). "This APD-induced diabetes has been confirmed in animal models; olanzapine and clozapine have been shown to decrease the plasma level of insulin and to cause hyperglycaemia and insulin resistance in rats." (PMID 29209160, 2017). "Our results showed that age, diabetes duration, and insulin treatment were independently associated with DPN, as has been previously reported." (PMID 28409160, 2017). "In this model, insulin-dependent diabetes was not achieved solely through STZ administration, as is seen in the rat and mouse, where STZ reproducibly leads to β-cell depletion and a state of insulin-deficient diabetes." (PMID 28093504, 2017). "In the meantime, their dietary benefits appear to be extended to enhancing insulin sensitivity that is often linked to obesity and the development of diabetes." (PMID 29023424, 2017). "Death of β cells led to the release of insulin stores in these cells, causing the observed hypoglycemia followed by onset of diabetes within 24 h." (PMID 28836097, 2017).
diabetes (continued). "In both mouse and human, failure of the skeletal muscle to appropriately respond to insulin is a hallmark of pre-diabetes, insulin resistance, and T2D." (PMID 29209279, 2017). "Surprisingly, deletion of MANF in mice leads to a progressive postnatal reduction of pancreatic β-cells followed by insulin-deficient diabetes." (PMID 29082311, 2017). "Increasing levels of A1c over time were associated with Hispanic ethnicity, number of years since diabetes diagnosis, and both insulin use at enrollment and insulin use over time." (PMID 28504709, 2017). "We also examined the expression of the insulin gene because marginal maternal zinc status is associated with impaired glucose tolerance and increased susceptibility to diabetes." (PMID 28837703, 2017). "Diabetes is caused by glycation of insulin and insulin is an essential growth factor present in the brain." (PMID 28593141, 2017). "We also analyzed participants’ β-cell function and insulin sensitivity to investigate the mechanism underlying the effect of alcohol on incident diabetes." (PMID 28779170, 2017). "Smoking is also a major risk factor for diabetes because it decreases insulin secretion and increases insulin resistance." (PMID 28706954, 2017). "Diabetes mellitus is a metabolic disease that is defined by relative or absolute deficiency of insulin secretion." (PMID 28497094, 2017). "The loss of insulin sensitivity is generally associated with persistent hyperglycemia (diabetes), hyperinsulinemia, fatty acids and/or lipid dysregulation which are often prevalent under obesity conditions." (PMID 29023424, 2017). "In diabetic patients, resveratrol was able to increase insulin sensitivity, decrease blood glucose levels, and positively regulate several other biomarkers associated with diabetes." (PMID 28989978, 2017). "Defective insulin secretion underlies all forms of diabetes mellitus, a disease that now affects more than 422 million individuals worldwide (World Health Organization)." (PMID 28377501, 2017). "Diabetes mellitus is a group of metabolic disorders associated with hyperglycaemia caused by defects in insulin secretion and/or action." (PMID 28531110, 2017). "A recent meta-analysis of double-blind randomized controlled trials supplementing Mg (12 in diabetics and 6 in those with high risk of diabetes) showed improved glucose parameters in diabetics and improved insulin-sensitivity in pre-diabetics." (PMID 29093983, 2017). "Diabetes mellitus is a chronic disease characterized by hyperglycaemia resulting from the defects in either insulin secretion or insulin action (American Diabetes Association, 2014 ▶)." (PMID 28348974, 2017). "The results suggested that higher insulin and glycol-hemoglobin levels were associated with diabetes-related cognitive dysfunction." (PMID 29445549, 2017). "We have already shown that glucose levels interact with what is to date the most important diabetes-associated common SNP in TCF7L2 to affect insulin secretion." (PMID 29138452, 2017). "The authors pointed out the interaction between insulin and the estrogen signaling and the effect of hyperglycemia on the expression and activity of estrogen receptors as mechanisms underlying the diabetes-related impairment of endothelium in diabetic women." (PMID 28316624, 2017). "The strong associations between self-reported diabetes and insulin, GIP, and PP found in this study are biologically expected given the critical roles that they play in glucose transport and metabolism." (PMID 28753646, 2017). "Smoking is a major risk factor for diabetes mellitus, mainly due to decreased insulin secretion and increased insulin resistance." (PMID 28706954, 2017). "Diabetes mellitus (DM) is a heterogeneous disease, characterized by chronic hyperglycaemia caused by defects in insulin secretion, insulin action, or both, resulting in impaired function in carbohydrate, lipid, and protein metabolism." (PMID 28298934, 2017).
diabetes (continued). "Diabetes is caused by a disorder of insulin secretion, reduced insulin sensitivity (insulin resistance) or a combination of both factors." (PMID 37168685, 2017). "Antidepressant drugs such as SSRIs and MAOIs are also reported to be associated with hypoglycemia, especially in patients with diabetes who are taking insulin." (PMID 28148284, 2017). "High-quality studies of glucose–insulin homeostasis measures monitored in well-defined and controlled populations are needed to further clarify the effects of 100 % fruit juice on diabetes risk as evaluated by these biomarkers." (PMID 29299307, 2017). "Type 1 diabetes mellitus is characterized by progressive loss of pancreatic β-cells, leading to a life-long dependence on exogenous insulin." (PMID 27974246, 2017). "Associations between diabetes/insulin treatment and clinicopathological subtypes were analyzed using multivariable logistic regression." (PMID 28076434, 2017). "Although estrogen per se is known to have insulin-sensitizing properties and to have a protective effect on pancreatic ß-cells, associations between estrogen levels and diabetes are conflicting." (PMID 28384295, 2017). "Insulin is a high-risk, critical medicine widely used in the treatment of diabetes mellitus, where inappropriate use can lead to poor glycaemic control, patient harm or even death." (PMID 28852529, 2017). "Animal studies demonstrate that genetic deficiency of the H2O2-scavenging enzyme catalase triggers adipose tissue oxidative stress, deterioration of insulin sensitivity and susceptibility to diabetes." (PMID 28545081, 2017). "Type 1 diabetes mellitus is a progressive disease caused by the destruction of pancreatic β-cells, resulting in insulin dependency and hyperglycemia." (PMID 29073149, 2017). "Reported data represents the observed association between use of insulin secretagogues preceding breast cancer diagnosis and GM-CSF, G-CSF and IL-7 profiles at the time of cancer diagnosis in women with diabetes mellitus." (PMID 28275660, 2017). "Serum Mg concentration was negatively associated with diabetes, BMI, serum glucose, serum insulin, HbA1c, and HOMA-IR." (PMID 28304338, 2017). "It was previously shown that even in young healthy adults, selective suppression of SWS causes pronounced decrease of insulin sensitivity, reduced glucose tolerance, and higher diabetes risk." (PMID 29164122, 2017). "There are two causes of Diabetes Mellitus, the first one is the abnormal production of insulin by the pancreas (Type I), while the second cause is related to inadequate cells action to insulin (Type II)." (PMID 28974212, 2017). "We then investigated if the HNF4A mutation or diabetes status impeded the initial in vitro maturation steps of the differentiated insulin+ cells." (PMID 28684784, 2017). "Treatment with insulin to tightly control glucose can reduce the risk of long term complications of diabetes but also increases risk of hypoglycemia (low blood glucose)." (PMID 28993722, 2017). "An increase in mitochondrial function has been associated with a reduction in diabetes and obesity outcomes, and exercise has a major impact on both mitochondrial function and insulin sensitivity in skeletal muscle." (PMID 28199417, 2017). "Patients with diabetes show increased urinary magnesium loss, caused by hyperglycaemia, hyperfiltration or a direct effect of insulin on magnesium channels in the kidney." (PMID 28224192, 2017). "Significantly, increased number of β cells is observed in response to elevated demand of insulin in several rodent models of obesity and diabetes, and the main mechanism underlying this is the proliferation of fully differentiated β cells." (PMID 28845211, 2017). "Compared with white individuals, the earlier and faster increases in FPG among South Asians suggest that using the standard diabetes diagnosis cut-off will find higher risk people who have advanced deterioration of both insulin sensitivity and secretion." (PMID 28409212, 2017).